LCN2 (lipocalin 2)
Diseases named in the same sentence as LCN2 in open-access papers (continued):
Sharing a sentence is not in itself a finding about the gene and the disease.
Anxiety (continued). "This blockade markedly decreased serum and central LCN2 concentrations in CRS mice and attenuated anxiety-like behaviors." (PMID 38589429, 2024). "Therefore, LCN2 may be a therapeutic target to combat anxiety induced by stress." (PMID 34179014, 2021). "The present study found that overexpression of lipocalin 2 in the brain evoked PTSD-like behaviors such as social avoidance and anxiety-like behaviors." (PMID 34565419, 2021). "More importantly, mice pretreated with vagotomy of the hepatic branch were resilient to chemogenetic activation, as shown by unchanged serum LCN2 and the absence of anxiety-like behaviors upon DMX stimulation." (PMID 38589429, 2024). "The excitation of the nodose ganglion neurons did not affect liver LCN2 level or induce anxiety-like behaviors in naïve mice." (PMID 38589429, 2024). "More importantly, chemogenetic inhibition of hepatic afferent nodose ganglia during CRS episodes cannot reverse the liver LCN2 surge and did not help to relieve anxiety-like behaviors in CRS mice." (PMID 38589429, 2024). "In order to assess the effects of aging in animal behavior, and in the absence of LCN2, Wt and LCN2-null mice were aged until 12- and 18-months of age, and evaluated for anxiety, depressive-like and cognitive behavioral dimensions." (PMID 37168715, 2023). "To disclose the importance of LCN2 in CORT-induced behavioral deficits, as others have described, we performed a behavior analysis after 28 days of CORT administration, which included an assessment of anxiety-like behaviors and of contextual discrimination." (PMID 37958520, 2023). "Overall, these results suggest that, along with the process of aging, a reduction in anxiety behavior occurs in the absence of LCN2." (PMID 37168715, 2023). "In the present study, we evaluated the impact of aging in several dimensions of animal behavior, including mood, anxiety and cognition, and upon the absence of LCN2." (PMID 37168715, 2023). "Importantly, overexpression of lipocalin 2 in the brain also elicited PTSD-like behaviors, such as social avoidance and anxiety-like behaviors." (PMID 34565419, 2021). "In line with this, the ablation of Lcn2 gene proved deleterious and promoted a stress-induced increase in spine density, which correlated with higher excitability of CA1 neurons and stress-induced anxiety." (PMID 33613327, 2021). "Furthermore, overexpression of lipocalin 2 in the brain also elicited PTSD-like behaviors, such as social avoidance and anxiety-like behaviors." (PMID 34565419, 2021). "Specifically, we found that running is sufficient to overcome the deficits in cell proliferation and differentiation observed in the absence of LCN2, which was accompanied by a partial improved anxiety and reversion of contextual discriminative behaviours." (PMID 30733506, 2019). "Interestingly, while young LCN2-KO mice (aged between two and three months) showed anxiety-like behavior under control conditions, no anxiety-like behavior was observed in aged LCN2-KO mice (twelve months old)." (PMID 41007258, 2025). "Moreover, other vagal afferent projecting brain regions including NTS and AP were also selectively activated by chemogenetic approaches, which did not elicit circulating LCN2 peak or anxiety-like behaviors." (PMID 38589429, 2024). "In addition, LCN2 KO mice exhibit anxiety-like behavior without any additional intervention." (PMID 41007258, 2025). "The intraperitoneal injection of LCN2 did not affect DMX activity but reversed the effect of chemogenetic manipulation, recapitulating anxiety-like behaviors." (PMID 38589429, 2024). "The genetic knockdown manipulation of SLC22A17 in mPFC effectively attenuated LCN2-mediated anxiety-like behaviors, whilst the receptor ablation in hippocampus or BLA did not prevented the LCN2 effect." (PMID 38589429, 2024).
Anxiety (continued). "A lack of LCN2 was recently described to induce deficits in NSC proliferation and commitment by modulating the levels of oxidative stress, with an impact on hippocampal-dependent contextual fear discrimination and anxiety." (PMID 37958520, 2023).
Parkinson disease (26 papers, 2010 to 2026). A progressive degenerative disorder of the central nervous system characterized by loss of dopamine producing neurons in the substantia nigra and the presence of Lewy bodies in the substantia nigra and locus coeruleus. "Increase in LCN2 protein level was detected in human post-mortem brain tissues of Alzheimer’s disease, Parkinson’s disease (PD), and multiple sclerosis patients." (PMID 35440572, 2022). "The level of lipocalin-2 was found to be increased in patients with AD and Parkinson’s disease (PD); the patient’s pathophysiology was also aggravated along the lipocalin-2 levels." (PMID 36558562, 2022). "Nonetheless, all the evidence suggests that PROS1, PPBP, and LCN2 are known to be well detectable in vivo in blood and thus represents a potentially valuable source of biomarkers for Parkinson’s diseases." (PMID 36189230, 2022). "Receiver operating characteristic (ROC) of PPBP, PROS1, and LCN2 for prediction of Parkinson’s disease and healthy controls." (PMID 36189230, 2022). "A recent study also reported that astrocytes from patients with Parkinson’s disease are more responsive to lipocalin 2 stimulation for reactive astrocytosis." (PMID 34565419, 2021). "A recent study reported that Parkinson’s disease patients are more responsive to lipocalin-2 stimulation for reactive astrocytosis." (PMID 35010945, 2021). "In the CNS, increased LCN2 is observed in patients with neurodegenerative disorders such as AD and Parkinson disease, and ultimately aggravates the neuropathophysiology of such diseases." (PMID 33945675, 2021). "Several studies have shown that the level of LCN2 in the blood increases in patients with neurological diseases, including AD, mild cognitive impairment, and Parkinson's disease." (PMID 33945675, 2021). "The researcher can also refine the search criteria (putamen) by adding more terms, such as a gene name (lcn2) or the name of the disease (Parkinson's)." (PMID 21176225, 2010). "Once the region of interest has been identified, the researcher would then like to search for other image data that show expression patterns for gene lcn2, were collected to study Parkinson's disease, and contain the region of interest." (PMID 21176225, 2010). "Consider a researcher who has collected a series of slices for an experiment for Parkinson's disease in relation to the Lipocalin-2 gene (lcn2) using a mouse model." (PMID 21176225, 2010). "Additionally, increased levels of LCN2 have also been found in the substantia nigra of patients with Parkinson’s disease." (PMID 38673873, 2024). "LCN2 also carries iron into cells, which may help explain why certain Parkinson’s disease patients have an excess of iron in their substantia nigra." (PMID 37240031, 2023).
chronic heart failure (24 papers, 2012 to 2026). "Molecules released by neutrophils such as neutrophil gelatinase associated lipocalin (NGAL or LCN2) have been linked to adverse outcomes in chronic heart failure." (PMID 35053159, 2021).
type 1 diabetes (24 papers, 2013 to 2025). "We predominantly used the MLDS model to investigate the role of LCN2 in the pathogenesis of diabetic encephalopathy because it represents a model of mild type 1 diabetes and closely resembles the pathophysiology observed in human patients." (PMID 30761088, 2019). "Also, results also showed that Type I diabetes was made more active by the downregulation of LCN2." (PMID 40171220, 2025). "The first aim of this study was to investigate plasma levels of FGF21, Cystatin C, lipocalin 2 and MMP-9 in children and adolescents with different duration of type 1 diabetes." (PMID 38932813, 2024). "This study aimed to investigate plasma levels of FGF21, Cystatin C, lipocalin-2, and MMP-9 in children and adolescents with different duration of type 1 diabetes and possible correlation to HbA1c to identify potential biomarkers of future complication development." (PMID 38932813, 2024). "In a sub-group of patients with type 1 diabetes blood was drawn at time of and after diagnosis, with a mean time between samplings 1.3 ± 0.5 years (n = 42), the trajectory of circulating Cystatin C, MMP-9, lipocalin-2 and FGF21 was analysed." (PMID 38932813, 2024).
endothelial dysfunction (23 papers, 2014 to 2026). In vascular diseases, endothelial dysfunction is a systemic pathological state of the endothelium (the inner lining of blood vessels) and can be broadly defined as an imbalance between vasodilating and vasoconstricting substances produced by (or acting on) the endothelium. "In murine models, LCN2 deficiency protects against high-fat diet-induced endothelial dysfunction, preserves eNOS dimerization, and maintains NO-mediated vasodilation." (PMID 41303567, 2025). "elucidated that LCN2 buildup in arteries causes endothelial dysfunction by upsetting the vascular system and changing the polyamine balance." (PMID 39558976, 2024). "LA exhibits high-affinity binding to lipocalin-2, a proinflammatory adipokine that causes vascular inflammation and endothelial dysfunction in mice." (PMID 39139767, 2024). "In two other studies, LCN2-deficient mice were protected from dietary challenge-induced endothelial dysfunction, reflected by enhanced blood pressure, impaired endothelium-dependent relaxation, and augmented endothelium-dependent contractions." (PMID 32544571, 2020). "Administration of lipocalin-2 could promote endothelial dysfunction, induce adipose tissue inflammation, and cause abnormal vasodilator response in high-fat diet-induced obese mice." (PMID 29731737, 2018). "In particular the proinflammatory adipokine lipocalin-2 may be important as this hormone is upregulated in obese humans and rodents, and accumulation of deamidated lipocalin-2 in arteries causes vascular inflammation and endothelial dysfunction in dietary obese mice." (PMID 26041981, 2015). "Studies have demonstrated that LCN2 induces endothelial dysfunction by promoting eNOS uncoupling and COX production." (PMID 39558976, 2024). "The IPA analysis clearly suggested a link between LCN2 and several brain processes and functions, such as endothelial dysfunction, extravasation, migration of endothelial cells and activation of astrocytes." (PMID 37496672, 2023). "It has also been described that LCN2 is critically involved in diet-induced endothelial dysfunction by influencing cytochrome P450 2 C9 activity." (PMID 38203346, 2023). "The administration of the deamidated recombinant LCN2 in mice has led to severe endothelial dysfunction, compared with WT recombinant LCN2 administration." (PMID 32544571, 2020). "Given their possible involvement in key molecular pathways—ranging from oxidative stress and low-grade inflammation to endothelial dysfunction, altered mineral metabolism and tissue remodeling—RBP4, LCN2, ApoM, Klotho and MGP represent more than isolated biomarkers." (PMID 41303567, 2025).
lupus (23 papers, 2013 to 2025). "On the contrary, a recent study by Mike and colleagues assessing the role of LCN2 on the neurobehavioral manifestations of a mouse lupus model found LCN2 deficiency in Sle1,3 mice attenuated the depressive-like phenotype as well as memory impairments that are characteristic of the model." (PMID 34039300, 2021). "Our study identified a localized and differentiated role of LCN2 in target organ injury in a robust spontaneous lupus model." (PMID 39399497, 2024). "We also observed a decrease in astrocyte activation in the hippocampus of LCN2-KO mice, supporting an effect of LCN2 in the lupus hippocampus." (PMID 39399497, 2024). "The effects of LCN2 on immune cell recruitment into the brain and skin provide an important look into the possible mechanism of action of LCN2 in these common lupus manifestations." (PMID 39399497, 2024). "When LCN2−/− mice were injected with pristane to induce lupus, there were reduced glomerular IgG and C3 deposits, macrophage and neutrophil infiltration, and less frequency and number of Th1 cells." (PMID 38164134, 2023). "Further studies on the identification of biomarkers for LPS tolerance and Lcn-2 administration in lupus are needed." (PMID 31514375, 2019). "In this study, we found that LCN2 deficiency significantly attenuates neuropsychiatric and cutaneous disease in MRL/lpr lupus prone mice, likely by decreasing local infiltration of immune cells into the brain and skin and reducing astrocyte activation in the hippocampus." (PMID 39399497, 2024). "Hence, we propose the use of Lcn-2 to remedy LPS tolerance especially in lupus with bacterial infection." (PMID 31514375, 2019). "In addition, rLcn-2 improved renal function, reduced liver injury and attenuated serum cytokines only in FcGRIIb-/- mice suggesting the different in Lcn-2 requirement between WT and FcGRIIb-/- lupus mice." (PMID 31514375, 2019). "Urinary LCN2 levels were higher in systemic lupus erythematosus (SLE) patients compared to healthy controls." (PMID 39403549, 2024). "Interestingly, LCN2 has also been previously proposed as a potential disease biomarker in the autoimmune disease systemic lupus erythematosus (SLE), as elevated levels of anti-LCN2 were detected in serum samples from patients with SLE." (PMID 28122643, 2017). "Unlike patients with lupus, MRL/lpr mice do not experience discrete flares or disease exacerbations but rather progressive disease; consequently, quantifying real-time LCN2 expression is challenging due to lower LCN2 expression during chronic inflammation." (PMID 39399497, 2024).
bladder cancer (22 papers, 2012 to 2025). "However, the underlying mechanism by which LCN2 promotes bladder cancer needs to be explored in the future." (PMID 37684641, 2023). "In bladder cancer, H3 K18 lactylation increases the expression of the oncogene lipocalin- 2 (LCN2), facilitating tumorigenesis." (PMID 40295451, 2025). "Nonetheless, the precise processes by which LCN2 facilitates bladder cancer progression have yet to be completely clarified." (PMID 40295451, 2025). "H3K18la is enriched at the LCN2 promoter, and high LCN2 expression promotes bladder cancer progression." (PMID 39417674, 2024). "The circXRN2-Hippo pathway regulatory axis further modulates tumor progression by inhibiting H3K18 lactylation and LCN2 expression in human bladder cancer." (PMID 37684641, 2023). "In bladder cancer, the LCN2 methylation ratio of the CpG site on the promoter is also much lower in the tumor tissue than in the normal tissue." (PMID 27912767, 2016). "LCN2 has been applied as a tumor marker in bladder cancer and has been found to be higher in urine of patients’ diagnosed with non-papillary bladder cancer as compared to papillary bladder cancer." (PMID 27782193, 2016). "Normal human bladder tissue is known to express both S100A9 and lipocalin-2; in bladder cancer, expression of both increases." (PMID 25354343, 2014). "In addition, we found that LCN2 was upregulated in bladder cancer tissues compared to normal tissues and was closely related to bladder cancer progression in the TCGA database and Kaplan‒Meier Plotter database." (PMID 37684641, 2023). "Since H3K18la could regulate LCN2 expression, rescue experiments were carried out to verify the interaction between H3K18la and LCN2 in bladder cancer progression." (PMID 37684641, 2023). "In summary, our results suggested that LCN2 is directly regulated by H3K18 lactylation and serves as an oncogene in human bladder cancer." (PMID 37684641, 2023). "In bladder cancer, circular RNA circXRN2 interacts with speckle-type POZ (SPOP) to activate the Hippo signaling pathway, inhibiting H3K18la of the lipocalin-2 (LCN2) gene promoter region, thereby downregulating LCN2 expression and suppressing tumor progression." (PMID 40589733, 2025).
thyroid cancer (22 papers, 2010 to 2025). "Previous reports have demonstrated that LCN2 levels are increased in various cancers, such as breast, ovarian, colon, pancreatic, and thyroid cancer, and that LCN2 is associated with poor prognosis." (PMID 25467539, 2014). "Our data show that higher LCN2 expression (OR = 3.48; P = 0.029) is significantly associated with extrathyroidal extension, a prognostic factor that is strongly associate with progression of thyroid cancer." (PMID 29321030, 2018). "In thyroid cancer, the tumour-promoting effect of LCN2 was demonstrated in a nude mouse xenograft model." (PMID 40109857, 2025). "In a thyroid cancer mouse model, mice injected with LCN2-silenced FRO cells had lower tumor volumes, had lower tumor weights, and developed fewer tumors overall than the mice injected with nontransfected FRO cells." (PMID 32575507, 2020). "In thyroid cancer, colony formation assays revealed a decrease in cell proliferation following LCN2-siRNA-mediated silencing in LCN2-overexpressing human anaplastic thyroid cancer cells (FRO cells)." (PMID 32575507, 2020). "In contrast, LCN2 was reported to be highly expressed in thyroid carcinoma and the silencing of LCN2 attenuated cancer cell survival under conditions of serum deprivation." (PMID 33604288, 2020). "Consistent with our findings, LCN2 protein overexpression has previously been found in a small series of thyroid cancers." (PMID 29321030, 2018). "Functional studies in thyroid cancer cell lines also support this assumption; ectopic expression of LCN2 in thyroid cancer cell line leads to an increase of its metastatic behaviour." (PMID 29321030, 2018). "In thyroid cancer cells, serum withdrawal evoked apoptosis, and this was suppressed by the addition of conditioned medium containing LCN2." (PMID 27168162, 2016). "In thyroid carcinoma cells, the increases in apoptosis through the knockdown of LCN2 were found to be canceled by the addition of Ferric ions or iron-loaded transferrin." (PMID 27168162, 2016). "Lcn2 transcription has already been shown to be dependent on NF-κB activation in breast and thyroid cancer cells and NF-κB has been shown to bind to the Lcn2 promoter." (PMID 21649922, 2011). "Likewise, the downregulation of NF-κB in human thyroid carcinoma cells had resulted into a failure in growing the cancer cells and inability to grow the xenograft via downregulating LCN2." (PMID 34588926, 2021). "Three out of ten (30%) of the thyroid cancer cell lines showed gain of LCN2." (PMID 29321030, 2018). "Moreover, LCN2 expression has been proposed as an efficient marker for differentiating benign from malignant thyroid neoplasms." (PMID 27249794, 2016). "Gene expression values (normalized read counts) of C1QL1 (a), LCN2 (b), CRABP1 (c) and CILP (d) in differentiated thyroid cancer (DTC) and normal thyroid (NT) tissues available in The Cancer Genome Atlas (TCGA)." (PMID 29321030, 2018). "LCN2 expression levels were successful measured by qPCR in 86 DTC (14 FTC, 19 FVPTC and 53 PTC), 10 thyroid cancer cell lines, 18 FTA, and 16 matched thyroid normal tissues." (PMID 29321030, 2018). "A regression model was performed with C1QL1, LCN2, CRABP1 and CILP expression values for thyroid cancer prognostic factors: age of patients (> 45 years), tumour size (> 4 cm), and presence of extrathyroidal extension of the tumour." (PMID 29321030, 2018). "Additionally, the use of molecular data for predict the prognostic of thyroid cancer patients remains controversial and the identification of biomarkers with prognostic potential (as we describe here for C1QL1 and LCN2) can further improve the design of this kind of assays." (PMID 29321030, 2018).